NOTCH3 (notch receptor 3)
Diseases named in the same sentence as NOTCH3 in open-access papers (continued):
Sharing a sentence is not in itself a finding about the gene and the disease.
psoriasis (1 paper, 2021). An autoimmune condition characterized by red, well-delineated plaques with silvery scales that are usually on the extensor surfaces and scalp. "The relationship between the NOTCH3 polymorphism and psoriasis was analyzed using five genetic models: dominant (TC + CC vs. TT), recessive (CC vs. TT + TC), additive (CC vs. TT), heterozygote (TC vs. TT), and allelic (C vs. T)." (PMID 34575036, 2021). "Our study aimed at investigating the genetic aspect of psoriasis etiology and it focused especially on the NOTCH3 and PSMA6 polymorphisms." (PMID 34575036, 2021). "We made an interesting observation that in the individuals who were NOTCH3 CC homozygotes, the risk of psoriasis was almost a five-fold higher than in the individuals with other combinations of genotypes (OR = 4.76)." (PMID 34575036, 2021). "The aim of the study was to analyze the NOTCH3 (6746T>C) (rs1044009) and PSMA6 (-8C>G) (rs1048990) polymorphisms and their role in genetic susceptibility to psoriasis." (PMID 34575036, 2021). "We made an attempt to detect possible links between the NOTCH3 (6746T>C) and PSMA6 (-8C>G) polymorphisms and psoriasis in five genetic models: dominant, recessive, additive, heterozygote, and allelic." (PMID 34575036, 2021). "Therefore, our study made an attempt to find a possible association between the NOTCH3 as well as PSMA6 polymorphisms and genetic susceptibility to psoriasis." (PMID 34575036, 2021). "Similarly, no statistical correlations were found between the NOTCH3 polymorphism and psoriasis parameters." (PMID 34575036, 2021).
rapidly progressive glomerulonephritis (1 paper, 2020). Inflammation of the glomeruli that is characterized by a rapid loss in renal function with glomerular crescent formation observed on biopsy; it is often seen in patients with concomitant autoimmune disease, like Goodpasture's syndrome or systemic lupus erythematosus. "In conclusion, Notch3 inhibition might protect podocytes and decrease the PEC activation, suggesting a novel therapeutic strategy for FSGS and rapidly progressive glomerulonephritis (RPGN)." (PMID 33149805, 2020).
retinoblastoma (1 paper, 2016). A malignant tumor that originates in the nuclear layer of the retina. "Notch pathway components were present in WERI Rb1 and Y79 retinoblastoma lines, with Jag2 and DLL4 more highly expressed than other ligands, and Notch1 and Notch2 more abundant than Notch3." (PMID 27661116, 2016).
serous carcinomas (1 paper, 2023). "The higher expression of Notch 3 (>2 fold) was significantly associated with chemo-resistant serous carcinomas compared to the low-expressing group (58.3% vs. 15.4%), suggestive of the role of Notch 3 as a possibly valuable predictive marker for chemoresistance." (PMID 36768291, 2023).
serous ovarian tumor (1 paper, 2020). "Studies on independent sets of serous ovarian tumor samples have confirmed increased NOTCH3 copy number, increased NOTCH3 transcript levels, and increased NOTCH3 protein levels." (PMID 32525899, 2020).
small cell carcinoma (1 paper, 2013). A neuroendocrine carcinoma composed of small malignant cells which are often said to resemble "oat cells" under the microscope. "The expression of Notch3 in small cell carcinoma tissue was lower compared with that of the corresponding non-tumor tissue (P<0.01)." (PMID 23420695, 2013).
small intestinal adenocarcinomas (1 paper, 2020). "A previous study has reported that Notch3 expression is correlated with lower T stage and the absence of lymphovascular invasion in small intestinal adenocarcinomas." (PMID 32974155, 2020).
small-bowel cancers (1 paper, 2021).
spinocerebellar ataxia type 37 (1 paper, 2021). Spinocerebellar ataxia type 37 (SCA37) is a subtype of autosomal dominant cerebellar ataxia type 1 (ADCA type 1), characterized by a cerebellar syndrome along with altered vertical eye movements. "Mutations in the NOTCH3 gene may promote the clinical presentation of spinocerebellar ataxia type 37 caused by mutations in the DAB1 gene." (PMID 34222332, 2021).
systemic sclerosis (1 paper, 2020). A chronic disorder, possibly autoimmune, marked by excessive production of collagen which results in hardening and thickening of body tissues.
thrombophilia (1 paper, 2024). A condition characterized by an abnormally high level of thrombi. "We aimed to identify the variants of NOTCH3 and thrombophilia genes, and their complex interactions with other factors." (PMID 38935968, 2024).
thyroid tumor (1 paper, 2026). A benign or malignant neoplasm affecting the thyroid gland. "Our findings suggest that miR-1179 is a tumor suppressor gene and that its loss may contribute to thyroid tumor progression by promoting the expression of ELF3, NOTCH3, and CX3CL1." (PMID 42121903, 2026).
tongue cancer (1 paper, 2020). A malignant neoplasm affecting the tongue. "In tongue cancers NOTCH3 expression was higher in comparison to healthy adjacent tissue of isolated patient samples." (PMID 32796631, 2020). "In human tongue carcinoma the expression of NOTCH1 and NOTCH3 showed strong correlations with the clinical stage of the tumor." (PMID 32796631, 2020).
tongue SCCs (1 paper, 2016). "There was not much difference in the frequency of NOTCH3-positive CAFs in tumor stroma among tongue SCCs and other SCCs." (PMID 27124156, 2016).
uremia (1 paper, 2022). A clinical syndrome associated with the retention of renal waste products or uremic toxins in the blood. "Mice lacking Notch3 expression exhibited lower NF-κB activation in glomeruli associated to milder proteinuria, uremia and inflammatory infiltration." (PMID 35215234, 2022).
uterine cancer (1 paper, 2022). Primary or metastatic malignant neoplasm involving the uterine corpus and/or the cervix. "Multivariate analysis identified expression alterations of NOTCH3 and NOTCH4, as a significantly independent prognostic factor for overall survival in patients with uterine cancer." (PMID 35136410, 2022). "Expression alterations of NOTCH2, NOTCH3, NOTCH4, JAG2, and HES1 were evaluated as independent and significant prognostic factors for uterine cancer patients." (PMID 35136410, 2022). "NOTCH2, NOTCH3, NOTCH4, JAG2, and HES1 may be used as independent and significant prognostic factors for uterine cancer patients." (PMID 35136410, 2022).
Varicose veins (1 paper, 2019). Enlarged and tortuous veins. "Other studies have discovered associations between development of varicose veins and mutations of TIE2, NOTCH3, thrombomodulin, and transforming growth factor beta receptor, suggesting a genetic component in venous disease associated with PVC." (PMID 31921319, 2019).
vascular malformation (1 paper, 2025). A non-neoplastic disorder that is the result of defects of vascular morphogenesis. "In addition, CCM2 and NOTCH3 were reported to be associated with vascular malformations and multiple cerebral cavernous malformations." (PMID 40584829, 2025).
vascular parkinsonism (1 paper, 2022). A Parkinsonism that is characterized by postural instability, a broad-based gait with the absence of tremors of vascular origin. "A missense mutation c.1630C>T (p.R544C) on the NOTCH3 gene was identified on whole-exome sequencing, which confirmed the diagnosis of vascular parkinsonism secondary to CADASIL." (PMID 35082744, 2022).
Williams-Beuren syndrome (1 paper, 2022). "Using a combination of gene-targeted mice, tissues and cells from patients with Williams-Beuren syndrome, and targeting of elastin in human VSMCs, the authors identified VSMC-derived NOTCH3 signaling as a critical mediator of aortic hypermuscularization and loss of vascular patency." (PMID 35229725, 2022).
tumor (384 papers, 2009 to 2026). "Shu (2018) showed that the expression of miR-150-5p in the THP-1 line monocytes by inhibiting Notch3 caused a decrease in the expression of the CCR2 on tumor-associated monocyte cells." (PMID 40822140, 2025). "It has been proved that NOTCH3 signaling promotes the tumor growth and closely associated with the poor outcome in patients with CRC." (PMID 40796704, 2025). "High expression of NOTCH3 protein was correlated with tumor grade, invasion, metastasis, and shortened survival, whereas low expression of NOTCH3 mRNA was associated with longer survival in patients with unresectable PDAC." (PMID 39548190, 2025). "On the other hand, Notch3 polymorphism rs1043994, A > G was significantly associated with the expression of Notch3 protein in tumor tissue and increased the risk of CRC development." (PMID 41027955, 2025). "In GC, studies have shown that NOTCH3 is highly expressed in tumor tissues and is associated with survival and immune infiltration, but there is limited research on the mechanisms by which NOTCH3 influences the biological behavior of GC." (PMID 40940884, 2025). "The Notch 3 ligand Jagged-1, produced by tumor cells, is upregulated in human lung cancer-associated endothelial cells and inhibits the apoptosis induced by the altered Notch3 expression in tumor vasculature." (PMID 40429321, 2025). "There were seven distinct SNVs present in tumor DNA, with two of these also detected in the CaB34—NOTCH3 missense and FANCD2 synonymous mutation." (PMID 40497995, 2025). "NOTCH-3 acted as a tumor suppressor, its mutation caused tumor proliferation, invasion, and metastasis." (PMID 38750402, 2024). "Collectively, these findings and the demonstration that MUC1 associates with expression of ∆Np63, SOX2, and NOTCH3 in individual HNSCC tumor cells indicate that MUC1-C is a common effector of the HNSCC CSC state." (PMID 38619287, 2024). "In concert with these results, we report that MUC1 associates with ∆Np63, SOX2, and NOTCH3 expression in HNSCC tumor cells as determined by single-cell RNA sequencing (scRNA-seq) analysis." (PMID 38619287, 2024). "NOTCH3 is associated with more aggressive disease and poor prognosis, acting as a molecular switch in angiogenesis and the release from tumor dormancy." (PMID 39228892, 2024). "NOTCH3 is associated with tumor staging, lymph node and distant metastasis in this subtype, whereas NOTCH1-signaling correlates with poor prognosis and drives metastasis." (PMID 37860822, 2023). "We monitored tumor initiation every 2 days from day 60 and observed that loss of Notch3 induced a significant reduction of tumor-free survival." (PMID 36854682, 2023). "Genetically depleting Notch-3/4, or pharmacologically suppressing Notch signal by γ-secretase inhibitor ameliorated the stem cell phenotypes and tumor growth induced by KLF10 deficiency in PDAC cells." (PMID 37308977, 2023). "NOTCH3 is formerly implicated in angiogenesis, and recent findings indicated its roles in tumorigenesis, tumor maintenance and resistance to therapies." (PMID 37945567, 2023). "The downregulation of miR-483 expression in HCC patients’ tumor samples was associated with Notch 3 upregulation." (PMID 36980601, 2023). "Here, we have demonstrated that the expression of Notch3 was positively associated with the level of soluble tumor-derived chemotactic factors, such as CSF1, CXCL12 and CCL2, which are chemotactic stimulus for macrophage recruitment." (PMID 36647017, 2023). "In the mammary glands of Notch3-deficient mice, we observed accelerated tumor initiation and proliferation in a MMTV-Neu model." (PMID 36854682, 2023). "It was further demonstrated that in BC, Notch ligand/Notch3 is highly expressed in blood vessels and implicated in tumor angiogenesis." (PMID 35682974, 2022).
tumor (continued). "In contrast, NOTCH-3 acts as a tumor suppressor, in human breast cancer, with mutations resulting in elevated tumor proliferation, invasion, angiogenesis, epithelial-to-mesenchymal transition (EMT), and self-renewal of breast cancer stem-like cells." (PMID 36476410, 2022). "Statistical analysis showed that NOTCH3 expression was associated with gender, local recurrence, tumor resection, postoperative radiotherapy, WHO classification, and ATRX (P < 0.05)." (PMID 36382054, 2022). "When it comes to NOTCH3 alterations, including amplification and upregulation, other research has already found that they are highly associated with tumor invasiveness and poor survival." (PMID 35073251, 2022). "High NOTCH3 expression further negatively correlated with other, established and widely used predictive biomarkers for the success of ICIs, including high tumour mutation burden (TMB) and the innate anti-PD-1 resistance (IPRES) signature." (PMID 34944837, 2021). "The resistance of tumor cells to doxorubicin, a DNA topoisomerase II inhibitor, is associated with the activation of Notch3 signaling." (PMID 34195229, 2021). "The interactions between tumor cells and cancer-associated fibroblasts activate Notch3 signaling, thus promoting angiogenesis in oral squamous cell carcinoma." (PMID 34195229, 2021). "In clinical studies, high expression of Notch3 was found to be associated with tumor metastasis in OC, NSCLC, prostate carcinoma (PCa), HCC, PC and gallbladder carcinoma." (PMID 34195229, 2021). "Four Notch receptors have been associated with tumor growth (Notch1, Notch2, and Notch3), CSC regulation (Notch1, Notch2, Notch4), tumor invasion and metastasis (Notch1, Notch2, Notch3, Notch4), angiogenesis (Notch3), and drug resistance (Notch1 and Notch3)." (PMID 34207383, 2021). "First, the association of tumor-infiltrating immune cell (TIIC) abundance with NOTCH3 expression was estimated in GC from the Tumor IMmune Estimation Resource (TIMER) database." (PMID 33479597, 2020). "In the mouse prostate, endothelial Jagged1 was found to activate Notch3 in neighboring tumor cells, which has been associated with poor prognosis and high metastatic potential." (PMID 33198378, 2020). "Bernasconi-Elias and colleagues generated Notch3 inhibitory antibodies that exhibited strong antileukemic activity in cell lines as well as tumor xenografts with Notch3 activating mutations." (PMID 32211044, 2020). "Notch3 expression and signalling have also been linked to the promotion of cellular senescence and a tumour suppressor role of Notch3 has been proposed." (PMID 32210034, 2020). "Notch 3, which is critically involved with tumour-associated angiogenesis, appears to have a protumourigenic role in breast cancer, particularly highly angiogenic TNBC." (PMID 32575680, 2020). "Guo-Jun Zhang from Xiang’an Hospital of Xiamen University, China, and colleagues conducted a bioinformatics search for regulatory microRNAs that target the messenger RNA transcript encoding Notch3, a protein known to suppress tumor spread." (PMID 30109262, 2018). "Overall, the in vivo data supports our in vitro findings and suggests that tumor persistence after short EGFR TKI exposure is associated with induction of Notch3 and β-catenin." (PMID 30097569, 2018). "We further confirmed the up-regulation of Notch3 mRNA in purified tumour-associated endothelial cells from subcutanous injected LLC1 in Cdh5:CreERT2xTomato mice allowing FACS sorting of tumour-associated endothelial cells." (PMID 28719575, 2017). "This work provides a new insight into the role of Notch signaling in CAFs associated with tumor angiogenesis and the possibility of NOTCH3-targeted molecular therapy in OSCCs." (PMID 27124156, 2016). "To date, only very few studies reported the association of NOTCH3 gene polymorphism with tumor in human." (PMID 25738469, 2015).